TCL6 (T cell leukemia/lymphoma 6)
Synonyms: TCL6e1; TNG2; TNG1; TCL6148; LOC124903372
Gene: Long non-coding RNA gene on chromosome 14 (95,620,914 to 95,679,833, forward strand). Ensembl gene ENSG00000187621.
Diseases named in the same sentence as TCL6 in open-access papers:
TCL6 is named in the same sentence as 18 diseases in open-access papers, as found by Europe PMC text mining. Sharing a sentence is not in itself a finding about the gene and the disease. The quoted sentences say what the papers report.
breast carcinoma (8 papers, 2020 to 2022). "Contrarily, low expression of the lncRNA T cell leukemia/lymphoma 6 (TCL6) in breast cancer has been associated with worse prognosis in progesterone receptor (PR)-negative patients, attributed in part to tumor immune-escape, via regulation of immune-related pathways such JAK/STAT cascades." (PMID 34943820, 2021). "lncRNA TCL6, which was shown to correlate with immune cells, showed a poorer prognosis in patients with breast cancer." (PMID 36032107, 2022). "In breast cancer, lnc- T-cell leukemia/lymphoma 6 (TCL6) correlated with immune infiltration and is therefore considered a useful prognostic molecular marker." (PMID 36207500, 2022). "TCL6 had been demonstrated to be a potential tumor suppressor in breast cancer, hepatocellular carcinoma, renal cell carcinoma, and B-cell acute lymphoblastic leukemia." (PMID 34367239, 2021). "For example, lncRNA TCL6 is related to immune infiltration of breast cancer, indicating poorer survival time." (PMID 34316393, 2021). "In breast cancer, lncRNA T-cell leukemia/lymphoma 6 (TCL6) is correlated with the infiltration of CD8+ T cells, CD4+ T cells, neutrophils, DCs, and the frequency of tumor-infiltrating lymphocytes (TILs)." (PMID 33194608, 2020). "Low TCL6 expression is linked to a poor prognosis, particularly in progesterone receptor-negative (PR) and luminal B breast cancer patients." (PMID 36207500, 2022).
B-cell acute lymphoblastic leukemia (3 papers, 2021 to 2024). A neoplasm of lymphoblasts committed to the B-cell lineage, typically composed of small to medium-sized blast cells. "ACER3 coregulates cell proliferation and survival with ACER2 and plays an important role in leukemia development; while TCL6 is associated with clinical outcomes of B-cell acute lymphoblastic leukemia patients; TFDP2 plays core roles in apoptosis and cell proliferation." (PMID 34722498, 2021).
preeclampsia (3 papers, 2023 to 2025). Preeclampsia is a hypertensive disorder of pregnancy that is characterized by new-onset hypertension with proteinuria presenting after 20 weeks of gestation, and depending on mild or severe forms may initially present with severe headache, visual disturbances, and hyperreflexia. "One study found that the expression of lncRNA TCL6 in peripheral blood of pregnant women with preeclampsia was up-regulated." (PMID 40342081, 2025). "The TCL6 gene has been reported to be overexpressed in the placental tissue of women with preeclampsia, threatened miscarriage, or spontaneous abortion." (PMID 36768581, 2023).
T-cell leukemia (3 papers, 2018 to 2020). A malignant disease of the T-lymphocytes in the bone marrow, thymus, and/or blood. "Another lncRNA TCL6, named T-cell leukemia/lymphoma 6 (TCL6), from a region on chromosome 14q locus was found in T-cell leukemia." (PMID 30406146, 2018). "The most significant SNP marker at 14q32.13 (rs117410836) is located near an uncharacterized long non-coding RNA (lncRNA; LINC02318), GLRX5 (glutaredoxin 5), and members of the T-cell leukemia (TCL) gene family (TCL1A, TCL1B, and TCL6)." (PMID 30305637, 2018).
clear cell renal cell carcinoma (2 papers, 2017 to 2020). "Decreased TCL6 levels have been associated with poor prognosis in patients with clear cell renal cell carcinoma." (PMID 32977510, 2020).
hepatocellular carcinoma (2 papers, 2021). A malignant tumor that arises from hepatocytes. "TCL6 inhibits the development of lncRNA in cancer, and in hepatocellular carcinoma directly regulated the PI3K / AKT signaling pathway by binding to miR-106a-5p to affect cancer development." (PMID 34101736, 2021).
leukemia (2 papers, 2020 to 2021). A malignant (clonal) hematologic disorder, involving hematopoietic stem cells and characterized by the presence of primitive or atypical myeloid or lymphoid cells in the bone marrow and the blood. "It is interesting to detect the TCL6 in leukemia-specific MAEs, since it was recently reported that low TCL6 levels were associated with poor survival of B-cell ALL patient, through a link between TCL6, TCL1B, and the AKT1 pathway." (PMID 34722498, 2021).
myelodysplastic syndrome (2 papers, 2020 to 2023). A clonal hematopoietic disorder characterized by dysplasia and ineffective hematopoiesis in one or more of the hematopoietic cell lines. "The lncRNAs LOC101928834, H19, WT1-AS, TCL6, LEF1-AS1, EPB41L4A-AS1, PVT1, GAS5 and ZFAS were found to be relevant to myelodysplastic syndrome (MDS) pathogenesis and outcome." (PMID 36607351, 2023).
renal cell carcinoma (2 papers, 2020 to 2021). "In this report, we investigate the effect of T-cell leukemia lymphoma 6 (TCL6) on paclitaxel (PTX)-induced apoptosis in Renal cell carcinoma (RCC) cells." (PMID 32047545, 2020).
Cirrhosis (1 paper, 2019). A chronic disorder of the liver in which liver tissue becomes scarred and is partially replaced by regenerative nodules and fibrotic tissue resulting in loss of liver function. "The diagnostic performance of lnc-TCL6 in different clinical stages of cirrhosis was first evaluated in our study." (PMID 31857905, 2019). "Additionally, ROC curves were employed to observe the diagnostic capacity of lnc-TCL6 in distinguishing among the three CP classes of cirrhosis." (PMID 31857905, 2019). "Considering the diversity of clinical features of patients with cirrhosis, we divided the entire LC group into three classes according to CP score for further research and verified the corresponding diagnostic and predictive values of lnc-TCL6." (PMID 31857905, 2019). "The results made lnc-TCL6 a potential diagnostic tool that could not only distinguish patients with early-stage cirrhosis from healthy people, but also discriminate among different clinical stages in cirrhosis patients." (PMID 31857905, 2019). "The expression level of lnc-TCL6 in patients with CP-A cirrhosis was significantly elevated compared with the healthy controls (P = 0.014), HBV carriers (P = 0.014), and CHB patients (P = 0.044) but gradually declined through CP-B to CP-C." (PMID 31857905, 2019). "The results indicated that the diagnostic performance of lnc-TCL6 was independent of disease status, which made it an optimal diagnostic tool to identify different clinical stages of cirrhosis." (PMID 31857905, 2019). "Although the expression level of lnc-TCL6 in the whole HBV-related LC group was not significantly different from that in the healthy controls and HBV-infection group in our present research, the expression profile of lncRNAs should be explored in cirrhosis at various stages." (PMID 31857905, 2019).
lymphoma (1 paper, 2013). A malignant (clonal) proliferation of B- lymphocytes or T- lymphocytes which involves the lymph nodes, bone marrow and/or extranodal sites. "TCL6: T cell Leukemia/Lymphoma 6 (TCL6) is transcribed from a locus involved in translocations and inversions with T cell receptor (TCR)." (PMID 23887658, 2013).
pulmonary hypertension (1 paper, 2022). Increased pressure within the pulmonary circulation due to lung or heart disorder. "So far, we have not found any research on TCL6, KCNMB2-AS1, and AC099521.3 in pulmonary hypertension." (PMID 35958401, 2022).
renal carcinoma (1 paper, 2020). A carcinoma arising from the epithelium of the renal parenchyma or the renal pelvis. "The analysis of TANRIC platform showed that the level of miR-221 was significantly negatively correlated with TCL6 in renal cancer." (PMID 32047545, 2020). "And TCL6 expression is progressively reduced in advancing clinical stages of renal cancer." (PMID 32047545, 2020).
tumor (13 papers, 2017 to 2025). "TCL6 regulates tumor-associated B cells, CD8 + T cells, CD4 + T cells, neutrophils, and Dendritic cells (DCs)." (PMID 36207500, 2022). "Furthermore, TCL6 is associated with tumor-infiltrating lymphocytes (TILs) and immunological checkpoint markers, including PD-1, PD-L1, PD-L2, and CTLA-4." (PMID 36207500, 2022). "The lncRNA T-cell leukemia/lymphoma 6 (TCL6) expression was also positively correlated with tumor lymphocytic infiltration and PD-1, PD-L1, PD-L2 and CTLA-4 expression." (PMID 37835376, 2023). "H19, TCL6, CAM1-AS1, GAS5 and LOC389332 act as tumor-suppressors, and are instead, downregulated; in particular, H19 and TCL6 are negatively correlated with TNM stage, lymph node metastases and distant metastases." (PMID 37370817, 2023). "Specifically, TCL6 was positively correlated with tumor infiltration with immune cells, including CD8+ and CD4+ T lymphocytes, neutrophils, B and DCs, as well as with the expression of PD-1, PD-L1, PD-L2 and CTLA-4 immune checkpoint molecules." (PMID 34943820, 2021). "It is reported that lncRNA T-cell leukemia/lymphoma 6 (TCL6) is a tumor suppressor in human cancer." (PMID 36810034, 2023). "Both C12orf77 and TCL6 not only could inhibit tumor growth (T3 + T4 vs. T1 + T2) but also downexpressed in individuals with high levels of the pathologic stage, implying their negative roles in tumor development of ccRCC." (PMID 36438902, 2022). "lncRNA T cell leukemia/lymphoma 6 (TCL6) positively correlates with tumor-infiltrating lymphocyte (TIL) infiltration and immune checkpoint molecules such as cytotoxic T-cell lymphocyte-associated protein 4 (CTLA-4), programmed death receptor 1 (PD-1), and its ligand (PD-L1)." (PMID 35754846, 2022). "Previous study has showed that overexpressed of TCL6 could suppress the proliferation and growth of ccRCC cells and the expression of TCL6 was negatively linked with TNM stage of tumor, which was similar to our results." (PMID 30406146, 2018). "Similarly, TCL6 has also been shown to be involved in development of RCC as a tumor suppressor and interestingly, artificial increase of TCL6 in cancer cells sensitizes them to paclitaxel, which could pose a novel therapeutical opportunity." (PMID 36988708, 2023). "An increase in oncogenic lnRNAs lowers the percentage of apoptotic cells, which is on the contrary, enhanced by the forced expression of tumor suppressor lncRNAs, such as GAS5 and TCL6." (PMID 37370817, 2023).
cancer (8 papers, 2019 to 2024). A tumor composed of atypical neoplastic, often pleomorphic cells that invade other tissues. "We observed lncRNA TCL6 associated with survival in Her2+ve cancers in the TCGA cohort with a CI of 0.86." (PMID 36386805, 2022). "Overexpression of TCL6 in corresponding cancer cell lines impairs their oncogenic functions, such as cell proliferation and migration/invasion." (PMID 34367239, 2021). "We aimed to elucidate the potential mechanisms of TCL6 modulating survival of cancer cells after PTX treatment." (PMID 32047545, 2020). "The results revealed that TCL6 was significantly decreased in cancer versus normal tissues." (PMID 32047545, 2020). "The list of subtype-specific DM lncRNAs from the three subtypes contained previously defined epigenetically altered lncRNAs from other cancer types, for example, we observed the oncogenic lncRNAs LINC00312, PVT1, and TCL6, which are differentially methylated in at least one of the three subtypes." (PMID 30642353, 2019).
blood neoplasms (1 paper, 2021). "According to OpenArray results, LINC01268, HOXB-AS3, MEG3 and TCL6 transcripts were selected since deregulated in CD34+ stem/progenitor cells; further lncRNAs have been selected for their associations with myeloid differentiation and deregulation in blood neoplasms." (PMID 34638230, 2021).
TCL6 also shares sentences with these, for which no sentence is quoted: Hip dysplasia (1 paper); liver-cirrhosis (1).